ZIC1 (Zic family zinc finger 1)
Diseases named in the same sentence as ZIC1 in open-access papers (continued):
Sharing a sentence is not in itself a finding about the gene and the disease.
developmental delay (2 papers, 2026). "An 11-month-old female infant, born to unrelated Saudi parents, was referred to our facility with unilateral left coronal craniosynostosis, congenital microcephaly, global developmental delay, and a confirmed ZIC1 gene mutation." (PMID 41523225, 2026). "Clinical manifestations of ZIC1 mutations extend beyond isolated suture fusion to include microcephaly, corpus callosum agenesis, cerebellar dysplasia, ventriculomegaly, tethered cord, scoliosis, and global developmental delay." (PMID 41523225, 2026).
endometrial cancer (2 papers, 2011 to 2020). Primary or metastatic malignant neoplasm involving the endometrium (mucous membrane that lines the endometrial cavity). "Urine samples of endometrial cancer patients (n = 42) and healthy controls (n = 46) were separated into three fractions (full void urine, urine sediment, and urine supernatant) and tested for three DNA methylation markers (GHSR, SST, ZIC1)." (PMID 33143739, 2020).
head and neck carcinoma (2 papers, 2017 to 2025). A carcinoma that arises from the head and neck region. "The analysis of the occurrence of gene promoter methylation in head and neck carcinoma cell lines indicated that CXXC4, DACT2, HHIP, ZIC1, and ZIC4 are methylated in these tumors." (PMID 27553089, 2017). "Similarly, the epigenetic status of ZIC genes, particularly their promoter methylation patterns, provides insight into diagnosis, as seen with the hypermethylation of ZIC1 and ZIC4 in ovarian and head and neck cancers." (PMID 40952541, 2025). "Few studies investigated the epigenetic regulation of Shh signaling in head and neck carcinomas; thus, we aimed to assess whether known negative regulators of this pathway (HHIP, PTCH1, SUFU, ZIC1, ZIC4) undergo methylation in HNSCC." (PMID 27553089, 2017).
liposarcoma (2 papers, 2012 to 2014). A usually painless malignant tumor that arises from adipose tissue. "Recent studies have demonstrated that mutant ZIC1 or force overexpression of ZIC1 regulates the expression of p27 Kip 1 in mice cerebellar tissues and liposarcoma cells." (PMID 22799764, 2012). "In contrast, overexpression of ZIC1 in liposarcoma was found to promote cell proliferation and invasion." (PMID 22799764, 2012). "These genes include ZIC1, TOP2A, and AURKA, which have high expression levels across the liposarcoma spectrum." (PMID 25238053, 2014).
lung carcinoma (2 papers, 2012 to 2018). "For instance, ZIC1 expression was reported to be low or absent in gastrointestinal and lung cancer cell lines, and was found to suppress gastrointestinal cancer cell proliferation." (PMID 22799764, 2012).
malignant pleural mesothelioma (2 papers, 2014 to 2020). A malignant neoplasm that arises from mesothelial cells in the pleura and shows a diffuse growth pattern. "In addition, it is also revealed the tumor inhibition effect of ZIC1 in malignant pleural mesothelioma cells." (PMID 33097694, 2020).
microcephaly (2 papers, 2022 to 2026). A congenital or acquired developmental disorder in which the circumference of the head is smaller than normal for the person's age and sex. "We report an 11-month-old female infant with a ZIC1 mutation presenting with unilateral left coronal craniosynostosis, microcephaly, and multiple neurodevelopmental and systemic comorbidities." (PMID 41523225, 2026).
osteoporosis (2 papers, 2022). A condition of reduced bone mass, with decreased cortical thickness and a decrease in the number and size of the trabeculae of cancellous bone (but normal chemical composition), resulting in increased fracture incidence. "Studies have shown that ZIC1 promoter methylation was related to the etiology of postmenopausal osteoporosis, and patients with RA are at high risk of osteoporosis." (PMID 36342317, 2022). "This supposition is supported by higher ZIC1 expression in iliac bone biopsies from postmenopausal women with osteoporosis compared with age-matched control subjects, as well as strongly significant inverse correlation between ZIC1 mRNA levels and BMI-adjusted bone mineral density (BMD) (Z-score)." (PMID 35328378, 2022). "ZIC1 mRNA levels in biopsies from the iliac of postmenopausal women showed significant inverse correlation with BMD and were significantly higher in women with osteoporosis than in healthy controls." (PMID 35328378, 2022).
prostate carcinoma (2 papers, 2016 to 2023). A carcinoma that arises from epithelial cells of the prostate gland. "Interestingly, we found that ZIC1, ZIC2, ZIC4 and ZIC5 were all up-regulated in Gleason grade 3 embedded in GS 4 + 3 = 7 prostate cancer on RNA level." (PMID 27191985, 2016).
schizophrenia (2 papers, 2019 to 2024). A major psychotic disorder characterized by abnormalities in the perception or expression of reality. "Of these, Plscr4, Armc8, Zbtb38, Rbp1, Zic1, and Trpc1 have been linked to schizophrenia or schizophrenia-related disorders in previous studies." (PMID 31920576, 2019).
Alzheimer disease (1 paper, 2018). A progressive, neurodegenerative disease characterized by loss of function and death of nerve cells in several areas of the brain leading to loss of cognitive function such as memory and language. "We uncovered several promising tissue-specific regulatory TFs or genes for Alzheimer’s disease (e.g. ZIC1 and STX1B) and asthma (e.g. CSF3 and IL1RL1)." (PMID 29378629, 2018).
anal carcinoma (1 paper, 2021). "A cross‐sectional series of 176 tissue samples of anal cancer, AIN3, AIN2, AIN1 and control biopsies obtained in HIV‐negative women and men was tested for six methylation markers (ASCL1, LHX8, SST, WDR17, ZIC1 and ZNF582)." (PMID 33580586, 2021).
asthma (1 paper, 2018). "We uncovered several promising tissue-specific regulatory TFs or genes for AD (e.g. ZIC1 and STX1B) and asthma (e.g. CSF3 and IL1RL1) in our case studies." (PMID 29378629, 2018).
bladder tumor (1 paper, 2021). "Methylation levels of GHSR, SST, and ZIC1 were determined using paired bladder tumor tissues and cervical scrapes as a reference." (PMID 33572525, 2021). "Methylation levels of the markers GHSR, SST, and ZIC1 were determined in bladder tumor tissues, in both paired natural voided urine and nephrostomy urine." (PMID 33572525, 2021).
Cachexia (1 paper, 2023). Severe weight loss, wasting of muscle, loss of appetite, and general debility related to a chronic disease. "Similarly, the expression levels of the FFA β-oxidation gene carnitine palmitoyltransferase (Cpt1) and browning of WAT markers, including Cd137, Zic-1 and UCP-1, were increased compared with rats without cachexia in the control group (P < 0.01)." (PMID 36670439, 2023).
cerebellar disorder (1 paper, 2023). Diseases that affect the structure or function of the cerebellum. "ZIC1/2 are strong drivers of CGN maturation, and mutation of these genes is associated with cerebellar disorders, showing their importance in CGN development." (PMID 37092728, 2023).
ciliopathy (1 paper, 2025). A genetic disorder of the cellular cilia or the cilia anchoring structures, the basal bodies, or of ciliary function. "DWS is classified as part of the ciliopathy spectrum, with mutations in genes such as ZIC1, ZIC4, and FOXC1 identified in familial cases." (PMID 41585016, 2025).
colorectal tumor (1 paper, 2011). "To further investigate the relationship between ZIC1 expression and promoter hypermethylation, we analyzed ZIC1 mRNA expression and CpG site methylation status in primary colorectal tumor and adjacent non-tumor tissues by qRT-PCR and MSP, respectively." (PMID 21347233, 2011).
cyclopia (1 paper, 2014). "Dilution of zic-1 dsRNA with an equal amount of control dsRNA increased the penetrance of cyclopia and decreased the penetrance of headlessness." (PMID 24992682, 2014).
fibrosis (1 paper, 2025). the formation of excess fibrous connective tissue in an organ or tissue in a reparative or reactive process. "In the Radial Ischemia Preconditioning Fibrosis model, it inhibits epithelial-mesenchymal transition and alleviates fibrosis by targeting ZIC1." (PMID 40504789, 2025).
head and neck squamous cell carcinoma (1 paper, 2017). A squamous cell carcinoma that arises from any of the following anatomic sites: lip and oral cavity, nasal cavity, paranasal sinuses, pharynx, larynx, and salivary glands. "In summary, we report that CXXC4, DACT2, HHIP, ZIC1, and ZIC4 are methylated in head and neck squamous cell carcinomas." (PMID 27553089, 2017).
intraepithelial neoplasia (1 paper, 2015). A precancerous neoplastic process that affects the squamous, glandular, or transitional cell epithelium without evidence of invasion. "The positive predictive value of plasma Zic1 promoter methylation for the diagnosis of intraepithelial neoplasia and GC was 100%." (PMID 26207911, 2015). "The Zic1 promoter methylation rate in the plasma samples from the healthy control group was 0%, but it reached 54.0% in the intraepithelial neoplasia group and 60.6% in the GC group." (PMID 26207911, 2015).
multiple system atrophy (1 paper, 2022). Multiple system atrophy (MSA) is a neurodegenerative disorder characterized by autonomic failure (cardiovascular and/or urinary), parkinsonism, cerebellar impairment and corticospinal signs with a median survival of 6-9 years. "Since mutations of ZIC1 and ZIC4 and paraneoplastic autoantibodies directed against ZIC4 are associated with severe cerebellar dysfunction, we conducted immunohistochemical analyses in brain tissue of the frontal cortex and the cerebellum from 24 Multiple System Atrophy patients." (PMID 35997131, 2022).
Obesity (1 paper, 2015). Accumulation of substantial excess body fat. "LACA mice can provide advantages against C57BL/6 when studying genes such as Zic1 or Olig1 or their associated pathways, which can be explored clinically as alternative strategies for the treatment of obesity and associated co-morbidities." (PMID 26010905, 2015).
omodysplasia (1 paper, 2013). Omodysplasia is a rare skeletal dysplasia characterized by severe limb shortening and facial dysmorphism. "Other upregulated genes included GPC6 (loss of function mutations result in the short stature condition omodysplasia) as well as zinc finger protein of cerebellum 1 (ZIC1) and PCP4 both of which are known to be differentially expressed in tumours." (PMID 24148222, 2013).
tumor (26 papers, 2011 to 2025). "However, the molecular mechanism underlying ZIC1 participation in tumour progression remains unknown." (PMID 22799764, 2012). "A putative tumor suppressor, ZIC1, involved in neurogenesis, dorsal spinal cord development, and maturation of the cerebellum was shown to be hypermethylated and silenced in OvCa." (PMID 39456618, 2024). "As expected, OPC markers OLIG2, SOX9, and cell cycle genes CDK1, MKI67 are highest in the tumor core (early peak), while neuronal markers ZIC1, GABRA1, and mature oligodendrocyte marker MBP are highest in the GCL_N (late peak)." (PMID 36823172, 2023). "On the other hand, a small cluster apparently revealed tumor-specific hypomethylation of ANKRD34 and ZIC1 loci starting from considerably increased methylation in adN samples, although a further increase in the tumor samples would have been expected." (PMID 35628134, 2022). "In full void, methylation levels of GHSR, miR-129, PRDM14, SST and ZIC1 were significantly correlated to the matched tumor tissues." (PMID 32252299, 2020). "For urine supernatant, there was a significant correlation between methylation levels of MAL, PHACTR3, PRDM14, SST and ZIC1 and the matched tumor tissues." (PMID 32252299, 2020). "It appears that ZIC1 is aberrantly expressed in certain types of cancer and differentially functions as a tumour suppressor or oncogenic gene." (PMID 22799764, 2012). "Some of the hypermethylated genes in TET2-wt CMML have been directly or indirectly related to cell cycle arrest, tumor suppression or myeloid differentiation (ZIC1, WT1, WNK2, MRPL41, POU4F2)." (PMID 22328940, 2012). "Recently, ZIC1 has been documented to participate in the progression of human tumours including medulloblastoma, endometrial cancers, mesenchymal neoplasms and liposarcoma cancers." (PMID 22799764, 2012). "First, the transfection efficiency of our ZIC1 construct was confirmed by RT-PCR and western blot in tumor cell lines (HCT116 and HT29)." (PMID 21347233, 2011). "The level of ZIC1 mRNA was significantly decreased in most tumor tissues relative to adjacent non-tumor tissues (p = 0.0001, n = 24)." (PMID 21347233, 2011). "In addition, ZIC2 was reported to be an oncogene in ONGene database, while ZIC1 was listed as a tumor suppressor in TSGene database." (PMID 40952541, 2025). "ANKRD34B and ZIC1 were evaluated as candidate genes by pyrosequencing of 539 tissues, including 239 normal autopsy, 157 histopathologically tumor-adjacent normal, and 143 paired tumor kidney samples." (PMID 35628134, 2022). "An appropriate study design and methylation detection technique are required to demonstrate a possible epigenetic lineage of tumor cells, such as that indicated by a sequence of risk factor-increased methylation of ANKRD34B and/or ZIC1 in normal cells and a further increase in derived tumor cells." (PMID 35628134, 2022). "To investigate whether the circMTO1/ miR-541-5p /ZIC1 axis can serve as a promising therapeutic target, we constructed xenograft tumor models of nude mice by subcutaneously injecting them with SMMC-7721 cells." (PMID 34930906, 2021). "For example, ZIC1 could act as a tumor inhibitor gene and suppressed cell proliferation via inactivating p-Erk1/2 and p-Akt pathway." (PMID 33097694, 2020). "The results revealed no marked associations between the Zic1 promoter methylation rate and the clinical parameters, including tumor size, differentiation grade, lymph node status, tumor invasion depth and TNM stage (p > 0.05)." (PMID 26207911, 2015). "Growing evidence has shown that ZIC1 is involved in the progression of several tumours." (PMID 22799764, 2012). "The study of ZIC1 target genes may provide further insight into the possible mechanisms of ZIC1 serving as a tumor suppressor in CRCs." (PMID 21347233, 2011). "Our results suggest that ZIC1 may potentially function as a novel functional tumor suppressor in CRCs." (PMID 21347233, 2011).
tumor (continued). "We previously showed that ZIC1 may function as a tumour suppressor in gastrointestinal cancers." (PMID 22799764, 2012). "Among them, ZIC1 and SLC46A3 have been shown to function as tumor suppressors and ZIC1 was found to play an important role in the Wnt/β-catenin pathway and EMT." (PMID 34930906, 2021). "Gene expression comparison between U-118 MG cells and the tumor showed an increased expression of neuronal and neural stemness genes MAP2, NEUN, ROBO2, PAX6, ZIC1, ZEB2, as well as MYC and OCT4 in tumor." (PMID 33468253, 2021). "In the metastasis-associated neoplastic cell states, we detected robust expression of neural crest (ZIC1, OLIG3), mesenchymal (MSX2, GDF6), and metastasis-related (DKK2) genes in addition to adrenergic genes (e.g., PHOX2B) that were shared with primary tumor cell states." (PMID 41279557, 2025). "Compared with A375 cells, A375 xenograft tumor displayed an upregulation for glial and neuronal genes (GFAP, BDNF, MAP2, MTURN, ROBO2, SYT1 and TUBB3) and neural stemness genes (ASCL1, MSI1, PAX6, PDGFRA, SOX9, VIM, ZIC1/2)." (PMID 33468253, 2021). "For NKX6-2, SPAG6, ZIC1 and ZNF154, methylation frequencies in recurrence and progression tumours were marginally greater than their no-recurrence counterparts, and were overall broadly similar to the frequencies apparent in low/intermediate-grade tumours." (PMID 26332997, 2015). "Furthermore, we demonstrated that ZIC1 can suppress the expression of other novel genes (TACSTD2, ANGPT2, LAMB2, LAMB3 and MALAT1 etc.)related to tumor angiogenesis and metastasis." (PMID 21347233, 2011). "Furthermore, methylation of ZIC1 gene promoter is frequently detected in primary tumor tissues (85%, 34/40), but not in adjacent non-tumor tissues." (PMID 21347233, 2011). "The mean methylation level increase from no-recurrence to recurrence and progression tumours was not significant for NKX6-2, SPAG6, ZIC1 and ZNF154." (PMID 26332997, 2015).